TIMP1 (TIMP metallopeptidase inhibitor 1)
Diseases named in the same sentence as TIMP1 in open-access papers (continued):
Sharing a sentence is not in itself a finding about the gene and the disease.
tumor (continued). "TIMP-1 can stimulate cell proliferation, accelerating tumor invasion and metastasis, via important signaling pathways such as NOTCH and WNT, with recent reports demonstrating the poor prognostic value of TIMP-1-positive expression in solid cancers." (PMID 35328635, 2022). "Many studies have identified dysregulation of TIMP1 expressions contributed critically to pro-tumor inflammation initiation, matrix remodeling and fibrosis development." (PMID 34670584, 2021). "In this process, TIMP1 significantly increases the sensitivity of the liver to circulating tumour cells and creates a tumour microenvironment that promotes tumour liver metastasis." (PMID 35003085, 2021). "Our findings shed light on a novel TIMP-1 autocrine signaling network critical for the regulation of tumor cell metabolism and the survival of breast carcinoma." (PMID 34685701, 2021). "When the TIMP1 gene is highly expressed, tumor patients progress more after chemotherapy, suggesting that the upregulation of TIMP1 gene reduce chemotherapy sensitivity." (PMID 34957118, 2021). "CCL18+M1, CXCL9+M2, and TIMP1+M3 were enriched in tumor tissues and were regarded as TAMs, whereas SELENOP+M4, MMP7+M5, CHIT1+M6, and PPARG+M7 were enriched in normal tissues and considered as resident tissue macrophages (RTMs)." (PMID 34659209, 2021). "The most interesting finding in this context is the continuously decreasing expression of MMP-9 and TIMP-1 at the invasive front of the tumor periphery in CDV-infected xenografts over time, which accompanied the decelerated growth of infected neoplasms." (PMID 33808256, 2021). "Like MMP2, MMP9 also degrades ECM components of the basement membrane to help facilitate tumor invasion while TIMP1 regulates MMP9 activity." (PMID 33995488, 2021). "Among them, Mcl-1 and Bcl-2 exerted anti-apoptotic effects in HCC cells, c-Myc and VEGF showed strong pro-tumor growth effects, and TIMP-1 was involved in the regulation of HCC metastasis." (PMID 34408811, 2021). "TIMP-1-positive IHC staining was defined as a tumour cell positive percentage ≥25% (n = 1), weak or moderate staining intensity (n = 4) or immune risk score (IRS) ≥2 (n = 2)." (PMID 33628641, 2021). "The imbalance of MMP-2 and its inhibitors TIMP-1 contribute to tumor invasion and metastasis, and tumor progression." (PMID 35201460, 2021). "For this reason, the functions of TIMP-1, both oncogenic (activation of intracellular signaling pathways) and tumor suppressor (MMPs inhibition), as well as the mechanisms involved in the regulation of these functions, should be better understood." (PMID 34502227, 2021). "MMP10, 7, 13 and TIMP1 were reduced in cured mice compared to tumor bearing mice, while Krt5 and Cldn8 levels increased in cured mice." (PMID 34944584, 2021). "TIMP-1 is a tissue inhibitor of metalloproteinases endowed with cytokine activity, also involved in neoplasia." (PMID 34572929, 2021). "Based on its complex and controversial functions, the role of TIMP-1 in tumour progression is still debated." (PMID 33628641, 2021). "Tissue inhibitors of metalloproteinases (TIMPs) such as TIMP-1, which are endogenous inhibitors of MMPs, are important in tumor formation." (PMID 35003391, 2021). "For TIMP-1, the expression was generally reduced in PrCa, including specifically in the transition from benign to neoplastic disease, and was also decreased in the recurrent and metastatic forms of the disease." (PMID 33808504, 2021). "In almost all tumors TIMP-1, -2 and -3 expression was noted in the epithelial tumor cells also co-expressing CA-125." (PMID 35047406, 2021). "In summary, five candidate genes (TIMP1, SPARCL1, MYL9, TPM2, and CNN1) were finally characterized as the hub gene associated with tumor recurrence in CRC." (PMID 33897765, 2021). "At this time point, DH82-UV-CDVai neoplasms exhibited significantly larger peripheral TIMP-1 immunopositive areas than xenografts of all other groups (p < 0.0001)." (PMID 33808256, 2021).
tumor (continued). "Pan-cancer expression analysis results showed that ITLN1, TSPAN11, CXCL13, and GPRC5B were downregulated and TIMP1 was upregulated in most tumor samples, including COAD, which was consistent with the results of the TCGA and GEO cohorts." (PMID 33579281, 2021). "Fourthly, the aberrant glycosylation of TIMP-1 contributes to high invasive potential of cancer cells in the tumor microenvironment." (PMID 33628641, 2021). "All these studies corroborate the idea that the TIMP-1/CD63/β1-integrin complex modifies the behavior of different types of tumor cells, giving them the ability to migrate, proliferate, and survive." (PMID 34502227, 2021). "Tissue inhibitor of metalloproteinases-1 (TIMP-1) is involved in tumorigenesis, cancer progression, tumor growth, and apoptosis." (PMID 33925872, 2021). "Given this function, many studies were carried out to verify if TIMP-1 was able to interrupt processes such as tumor cell invasion and metastasis." (PMID 34502227, 2021). "We found that recombinant TIMP-1 and -2 can partially contrast the induction of pro-tumor/pro-angiogenic decidual-like polarization of NK cells by TGFβ." (PMID 34638439, 2021). "The present paper demonstrates that among all of the proteins tested in our investigations, serum M-CSF, CXCL-8, IL-6 and TIMP-1 are better biomarkers than the currently used, well-established classical tumor marker—CEA—in the diagnosis of CRC." (PMID 34071492, 2021). "The expression of OPG was higher in normal tissues, whereas that of galectin-3 and TIMP-1 was higher in tumor tissues." (PMID 34208730, 2021). "In detail, the expression level of TIMP1 in the tumour group was dramatically augmented with a fold change of 18.922 in Bredel Brain 2’s dataset." (PMID 34781885, 2021). "The diagnostic sensitivity of TIMP-1 was higher (61%) than that of the serum levels of other biomarkers (MMP-9—55%; TIMP-2—59%, MMP-2—46%) as well as the classical tumor markers (CEA and CA 19-9), and increased in combined use with CEA." (PMID 34071492, 2021). "The relevance of a reduced TIMP-1 expression on tumor progression is discussed controversially within the literature." (PMID 33808256, 2021). "The tumor/stroma TIMP-1 intensity ratio in the tissue has a particularly important predictive effect on tumor recurrence." (PMID 34323652, 2021). "Others showed that the TIMP1 gene derived from tumor cells creates a metastatic niche, to which circulating tumor cells cling and promote CRC metastasis." (PMID 34440739, 2021). "Regarding its MMP-independent functions, TIMP-1 can bind with cytokines, adhesion molecules, cell surface proteins and induce survival signals, simultaneously affecting tumour architecture and progression." (PMID 33628641, 2021). "To find any association of IFN signaling in tumor cells with mesenchymal phenotypes, we chose five well-established signature genes of the mesenchymal phenotype: CHI3L1, CD44, SERPINE1, TNC, and TIMP1." (PMID 34771447, 2021). "Five cell types, TIMP1+M3, S100A8+N3, TUBB+Mcyl, LAMP3+DC3, and TCL1A+pDC, all of which were enriched in MSC2, were positively associated with tumor progression (FDR < 0.05)." (PMID 34659209, 2021). "TIMP-1 has broad tumour-promoting activity (proangiogenesis, antiapoptosis; promotion of cell growth, and proliferation)." (PMID 33005257, 2020). "The coexpression of MMP-7 and TIMP-1 in tumour tissue reflects a high level of activation of the entire proteinase system, which indicates an increase in tumour growth and metastasis." (PMID 33005257, 2020). "A total of 78 (27.4%) GC patients had positive immunohistochemical staining for TIMP-1 in tumour tissues." (PMID 33005257, 2020). "Unfortunately, no study to date has investigated the correlation between serum/plasma levels of TIMP-1 and tumour tissue levels of TIMP-1 in GC patients." (PMID 33005257, 2020). "The role of TIMP-1 in tumour invasion and metastasis appears to be complex and, in some cases, even divergent." (PMID 33005257, 2020).
tumor (continued). "Despite its role as MMP inhibitor, TIMP-1 exerts also its function in promoting tumor proliferation and regulating metastatic potential through hepatocyte growth factor (HGF) induced by HIF-1α." (PMID 32982967, 2020). "Increased blood MMP-7 and TIMP-1 levels occur when the proteins enter the circulation from tumour tissues." (PMID 33005257, 2020). "TIMP1 can not only inhibit the hydrolysis of matrix protein but also promote the growth and metastasis of tumor cells." (PMID 33144895, 2020). "Both cell lines secreted Gm-csf, Tnf-α, Ccl-2, Ifn-γ, and IL-1α while Timp1 was uniquely secreted by the PyMT+ tumor line." (PMID 31941005, 2020). "Nevertheless, LCL-DOX inhibited statistically significant (by 40–60%) the expression of proteins involved in the anti-tumor response: TIMP-1, TIMP-2, IFN-γ, MIG, PF-4, and IL-12p70." (PMID 32340166, 2020). "Matrix metalloproteinase (MMPs) are involved in tumor invasion, and their activity is regulated by inhibitors such as tissue inhibitor metalloproteinase-1 (TIMP1)." (PMID 32117120, 2020). "Although this is an important tumor-suppressive function of TIMP-1, accumulating evidence has shown that TIMP-1 can elicit tumor-promoting effects via cell signaling independent of its MMP inhibitory activity." (PMID 32034211, 2020). "There are at least 23 MMPs and four types of TIMPs expressed in humans, but MMP-2, MMP-9, MMP-14, TIMP-1, and TIMP-2 are often associated with the tumor invasion process." (PMID 32669083, 2020). "It was emphasized that active MMP-3 becomes a potent activator of proMMP-9 in a tumor cell model only when its concentration exceeds that of TIMP-1." (PMID 32455575, 2020). "Clusters #2 and 3, which had high expression of mesenchymal genes including Vimentin, Timp1, and Twist1, were predominantly composed of recurrent tumor cells but had small populations of primary tumor cells." (PMID 33024122, 2020). "Among these genes, four genes (TIMP1, MAPK13, MAPKAPK2 and MAPKAPK3) are known to regulate cell proliferation, and MMP2 and MMP9 control tumour-associated tissue remodelling; PIK3CD is involved in the immune response, and AKT2 regulates tumourigenesis." (PMID 32999349, 2020). "The elevated TIMP1 levels in serum were related to lower tumor grade and shorter overall survival times of CRC patients." (PMID 32936304, 2020). "Numerous studies have shown that expression of TIMP1 is higher in either tumor tissue extracts or in blood from patients suffering from different tumor types 27-29." (PMID 32922541, 2020). "The MMP-independent activity of TIMP-1 provides the mechanisms for the tumor-promoting functions of TIMP-1 in angiogenesis, invasion, and metastasis." (PMID 31443242, 2019). "TIMP-1 expression was significantly higher in the matrix and perimatrix of the mucous membrane than in cancer tissue (p = 0.0093) and the tumor stroma compartment (p < 0.0001)." (PMID 31143300, 2019). "Our study has identified TIMP-1 as a potential determinant that modulates the tumor microenvironment, contributing to resistance against chemotherapy." (PMID 31443242, 2019). "It was concluded that the increase in MMP-2, TIMP-1 in tumor, and MMP-9 in stroma were characterized by a decrease in the odds ratio for 5-year survival." (PMID 31223594, 2019). "On the other hand, it has been validated that an imbalance between MMP-2, which regulates ECM degradation, and TIMP-1, its tissue inhibitor, plays an important role in tumour invasion and cancer metastasis." (PMID 31836811, 2019). "In our study, positive TIMP-1 expression was observed more frequently in neoplastic cells than in tumor stroma cells." (PMID 31143300, 2019). "In the multivariate analysis, the factors which influence 3-year survival included the changes in MMP-9 expression in the tumor and stroma, as well as TIMP-1 in the stroma." (PMID 31223594, 2019). "MMP-9 and TIMP-1 were identified in tumor cells and in the tumor stroma compartment, as well as in macroscopically healthy mucous membrane." (PMID 31143300, 2019).
tumor (continued). "We then tested the protein levels of TGF-β1, MMP9, and TIMP1 proteins, which were important for tumor metabolism and metastasis." (PMID 31244554, 2019). "It seems that higher expression values of MMP-9 in tumor and stroma for the N1+N2 stage in comparison to the N3 stage are the results of a constant high expression level of TIMP-1, which inhibits the release of metalloproteinase-9." (PMID 31223594, 2019). "Functionally, TIMP-1 is a multifunctional glycoprotein which can inhibit most matrix metalloproteinases (MMPs) and stimulate tumor growth as well as malignant transformation." (PMID 31481982, 2019). "TIMP-1 expression was higher in the matrix and perimatrix of normal tissue than in carcinoma tissue and tumor stroma, respectively." (PMID 31143300, 2019). "The changes in dynamics with increasing N stage indicate a decrease in MMP-9 expression both in tumor and stroma with a simultaneous increase of TIMP-1 expression." (PMID 31223594, 2019). "MMP activities are regulated by endogenous tissue inhibitors of metalloproteinases such as TIMP-1, being the MMP/TIMP imbalance important for the tumor cell survival." (PMID 31551765, 2019). "The difference in the expression of tumor-stroma (T-S) for TIMP-1 (P<0.0001) proved a higher involvement of TIMP-1 in tumor progression in a statistically significant way, which is confirmed by other researchers." (PMID 31223594, 2019). "Study has demonstrated inhibition of TIMP1-mediated tumor invasion and metastasis in many types of tumor cells." (PMID 30414611, 2018). "Cellular co-expression of TIMP-1 and CD63 as well as TIMP-1 and the tumor stem cell-related markers CD133 and Sox2 was investigated with immunofluorescence." (PMID 29523123, 2018). "It is interesting, therefore, that TSP-1 upregulates TIMP-1 expression in tumor cells suggesting that the stimulatory effect of TSP-1 on T cell expression of LRP1 also is mediated through TIMP-1." (PMID 29774033, 2018). "It has been reported that the dysregulation of IGF2 and TIMP1 results in tumor invasion and metastasis." (PMID 30344796, 2018). "Consistent with the bioinformatics predictions, MUC12 and NXPE1 presented a sequentially descending trend in expression with tumor progression, and TIMP1 presented a sequentially ascending trend." (PMID 29659199, 2018). "TIMP-1 KD clones were also more adherent in an adhesion assay confirming the tumor-promoting function of TIMP-1." (PMID 29507665, 2018). "A study based on literature search revealed that increased protein levels of TIMP1 in either tumor tissue extracts or in plasma from GC patients have a correlation with adverse outcomes." (PMID 30065754, 2018). "Our initial observations prompted us to further investigate the significance of this relationship between TIMP-1 and miR-125a-5p in human tumor samples derived from wedge biopsies or surgical resections." (PMID 29507665, 2018). "TIMP-1/CD63 co-expression was detected in tumor biopsies as well as in the organotypic and U87MG cell line-derived spheroids." (PMID 29523123, 2018). "Tissue inhibitor of metalloproteinase-1 (TIMP-1) expression in peritoneum invaded by tumour was only sparsely seen in the invasion zone between the tumour and normal peritoneal tissue and close to the inflammatory cells present." (PMID 29623449, 2018). "Some TIMP-1/CD133 co-expressing cells were detected in some of the tumor biopsies, in the corresponding organotypic spheroids and in the U87MG cell line-derived spheroids, although the majority of the CD133+ cells did not co-express TIMP-1." (PMID 29523123, 2018). "Similar to this, TIMP-1/Sox2 co-expressing cells were detected in some of the tumor biopsies and in the corresponding organotypic spheroids, although the majority of the Sox2+ cells did not co-express TIMP-1." (PMID 29523123, 2018). "The presence of TIMP-1 was only seen in the zone between tumour and peritoneal tissue and in the proximity of inflammatory cells." (PMID 29623449, 2018).
tumor (continued). "In this study, TIMP1 was demonstrated to up-regulate in PTC tumor tissue, which was in consistent with the previous study." (PMID 30414611, 2018). "NF-κB activation induced tumor development by increasing TIMP-1 expression in KrasG12D lung cancer model." (PMID 30486830, 2018). "Fundamental insights into how TIMP-1 prepares the liver microenvironment for the influx of tumor cells in PDAC have emerged only recently, largely owing to the elegant work of Grünwald and colleagues." (PMID 29903049, 2018). "TIMP-1 has been shown to protect tumor cells from chemotherapy-induced RCD both in the in vitro and in clinical experiments." (PMID 30583560, 2018). "While TIMP-1 has long been known to be overexpressed in PDAC, it has only recently become apparent that TIMP-1 strongly influences tumor progression by triggering pro-metastatic conditioning of the liver." (PMID 29903049, 2018). "Our work presented herein explored how SIRT1 suppressed TIMP1 by impeding the binding of transcription factor specificity protein 1 (Sp1) to the TIMP1 promoter (pTIMP1) as well as what molecular mechanisms contributed to the tumor-like invasion of RA FLSs." (PMID 29179491, 2017). "Later, researchers found that TIMP-1 also functions independently of MMP-9 to promote tumour growth and inhibit apoptosis." (PMID 29228747, 2017). "This is confirmed by the EGb-induced reduction in mRNA expression of TIMP1, Caspase9, Bad, Apaf1, Nrf2, Cat and Nox3 in the Tumor group." (PMID 29197355, 2017). "Despite the expected variability found in in vivo experiments, animals inoculated with both Timp1 silenced clones presented a lag time of 14 days for the appearance of tumor mass." (PMID 28430130, 2017). "Subsequent analysis using both mouse and human-specific ELISAs demonstrated that elevated TIMP-1 expression was present within murine host plasma and within the tumor cells themselves." (PMID 29137288, 2017). "It has been shown that tumor cell-derived tissue inhibitor of metalloproteinases-1 (TIMP1) plays a role in liver metastasis of PC." (PMID 28383487, 2017). "In vivo, Timp1 reduction was able to reduce dramatically tumor formation and the number of metastatic lung colonies." (PMID 28430130, 2017). "The univariate Cox regression analysis revealed that patients with preserved Rab37, low TIMP1 and PKCα overexpression, with late stage, larger tumor size status, lymph node metastases or distant organs metastases had an increased risk for poor outcome." (PMID 29312551, 2017). "Timp1 downregulation resulted in decreased anoikis resistance, clonogenicity, dacarbazine resistance, and in vivo tumor growth and lung colonization." (PMID 28430130, 2017). "One method to do this involves engineering the tumor tissue with expression vectors to enhance TIMP-1 production." (PMID 29262667, 2017). "Additional tumor explant sections are shown in Supplementary 2B with dual H&E and TIMP-1 staining for ease of distinguishing tumor deposits within the liver bed." (PMID 29137288, 2017). "We further demonstrate that expression of Rab37 suppresses tumor progression by mediating exocytosis of TIMP1 and TSP1 to inactivate extracellular metalloproteinase 9 and to inhibit tumor neovasculature respectively." (PMID 29312551, 2017). "These in vivo results further support the notion that Rab37 phosphorylation at T172 inactivates the Rab37-mediated TIMP1 secretion and thus promotes tumor metastases." (PMID 29312551, 2017). "In a previous study, we characterized the protein expression of the tissue inhibitor of metalloproteinases-1 (TIMP-1) in astrocytic brain tumors and found that the protein expression increased with tumor grade (World Health Organisation (WHO) grade II–IV)." (PMID 27619981, 2016). "In conclusion, higher expression of TIMP-1 is necessary for advancement of tumor diameter from pT1a to pT1b, and a process of tumor diameter extension beyond pT1 category needs the presence of MVI and high nuclear grade." (PMID 27019657, 2016).